CAMK1 (calcium/calmodulin dependent protein kinase I)
Description:
Calcium/calmodulin-dependent protein kinase that operates in the calcium-triggered CaMKK-CaMK1 signaling cascade and, upon calcium influx, regulates transcription activators activity, cell cycle, hormone production, cell differentiation, actin filament organization and neurite outgrowth. Recognizes the substrate consensus sequence [MVLIF]-x-R-x(2)-[ST]-x(3)-[MVLIF]. Regulates axonal extension and growth cone motility in hippocampal and cerebellar nerve cells. Upon NMDA receptor-mediated Ca(2+) elevation, promotes dendritic growth in hippocampal neurons and is essential in synapses for full long-term potentiation (LTP) and ERK2-dependent translational activation. Downstream of NMDA receptors, promotes the formation of spines and synapses in hippocampal neurons by phosphorylating ARHGEF7/BETAPIX on 'Ser-694', which results in the enhancement of ARHGEF7 activity and activation of RAC1. Promotes neuronal differentiation and neurite outgrowth by activation and phosphorylation of MARK2 on 'Ser-91', 'Ser-92', 'Ser-93' and 'Ser-294'. Promotes nuclear export of HDAC5 and binding to 14-3-3 by phosphorylation of 'Ser-259' and 'Ser-498' in the regulation of muscle cell differentiation. Regulates NUMB-mediated endocytosis by phosphorylation of NUMB on 'Ser-276' and 'Ser-295'. Involved in the regulation of basal and estrogen-stimulated migration of medulloblastoma cells through ARHGEF7/BETAPIX phosphorylation (By similarity). Is required for proper activation of cyclin-D1/CDK4 complex during G1 progression in diploid fibroblasts. Plays a role in K(+) and ANG2-mediated regulation of the aldosterone synthase (CYP11B2) to produce aldosterone in the adrenal cortex. Phosphorylates EIF4G3/eIF4GII. In vitro phosphorylates CREB1, ATF1, CFTR, MYL9 and SYN1/synapsin I.
Synonyms: CaMKI-alpha; CaMKI
Tractability: Small molecule: a structure with a bound ligand is known; a high-quality ligand is known; it belongs to a druggable protein family. PROTAC: UniProt records ubiquitination sites on it; ubiquitination databases record sites on it; its protein half-life has been measured; a small molecule that binds it is known.
Target class: Protein Kinase; CAMK protein kinase group; Enzyme; CAMK protein kinase CAMK1 family; Kinase
Chemical probes: CS640 (high quality)
Gene: Protein-coding gene on chromosome 3 (9,757,346 to 9,770,606, reverse strand). Ensembl gene ENSG00000134072.
Subcellular location: Cytoplasm; Nucleus
Subcellular location (Human Protein Atlas): Cytosol
Pathways (Reactome):
Neuronal System: Activation of RAC1 downstream of NMDARs; Negative regulation of NMDA receptor-mediated neuronal transmission
Gene Ontology:
Molecular function: protein binding; protein serine/threonine kinase activity; calcium/calmodulin-dependent protein kinase activity; calmodulin binding; ATP binding; protein kinase activity; protein serine kinase activity
Biological process: intracellular signal transduction; positive regulation of dendritic spine development; positive regulation of muscle cell differentiation; positive regulation of neuron projection development; positive regulation of protein export from nucleus; positive regulation of synapse structural plasticity; positive regulation of syncytium formation by plasma membrane fusion; positive regulation of transcription by RNA polymerase II; regulation of muscle cell differentiation; regulation of protein localization; regulation of synapse organization; signal transduction; regulation of neuron projection development
Cellular component: cytoplasm; cytosol; postsynaptic density; nucleus
Genetic constraint (gnomAD): Loss-of-function variants: 40 observed, 53.53 expected, observed/expected ratio (o/e) 0.75, 90% interval 0.58 to 0.97. The upper end of that interval is the gene's LOEUF score, 0.97, which puts it in group 4 of 6, group 1 being the genes least tolerant of losing a copy. Missense variants: 457 observed, 496.24 expected, observed/expected ratio (o/e) 0.92, 90% interval 0.85 to 1. Synonymous variants: 192 observed, 195.9 expected, observed/expected ratio (o/e) 0.98, 90% interval 0.87 to 1.11.
Homologues: Orthologues: chimpanzee CAMK1 (99% identical), rat Camk1 (97% identical), mouse Camk1 (97% identical), dog CAMK1 (96% identical), pig CAMK1 (96% identical), guinea pig CAMK1 (96% identical), macaque CAMK1 (95% identical), rabbit CAMK1 (85% identical), tropical clawed frog camk1 (82% identical), zebrafish camk1b (78% identical), zebrafish camk1a (76% identical), Caenorhabditis elegans cmk-1 (58% identical). Paralogues in human: CAMK1D (74% identical), CAMK1G (61% identical), PNCK (59% identical), CAMKV (42% identical), CAMK2G (39% identical), CAMK2D (39% identical), PSKH1 (38% identical), CAMK2A (38% identical), CAMK2B (38% identical), DCLK2 (37% identical), DCLK1 (37% identical), PSKH2 (36% identical), and 10 more.
Diseases named in the same sentence as CAMK1 in open-access papers:
CAMK1 is named in the same sentence as 27 diseases in open-access papers, as found by Europe PMC text mining. Sharing a sentence is not in itself a finding about the gene and the disease. The quoted sentences say what the papers report.
leukemia (4 papers, 2018 to 2025). A malignant (clonal) hematologic disorder, involving hematopoietic stem cells and characterized by the presence of primitive or atypical myeloid or lymphoid cells in the bone marrow and the blood. "Both Camk1 or Camk4 knockdown significantly prolonged the survival of xenografted mice and greatly inhibited leukemia development as determined by analysis of knockdown cells, human leukemic hCD45+ cells, and spleen size." (PMID 29482582, 2018). "Next, we tested the in vivo effect of knockdown of CAMK1 or CAMK4 expression in MV4-11 leukemia cells in transplanted NOD/SCID-IL2RG (NSG) mice." (PMID 29482582, 2018). "The knockdown of CAMK1 or CAMK4 in AML cell lines including MV4-11 cells and KASUMI-1 led to significant inhibition of cell growth, indicating that CAMKs are functionally essential for human leukemia cells." (PMID 29482582, 2018). "Though CAMK overexpression did not affect WT leukemia development, the kinase-inactive CAMK1 mutant and CAMKIV mutant were able to play dormant negative roles in leukemia development in vivo and in vitro." (PMID 29482582, 2018). "Because CAMK1 activity is tightly regulated by the calcium signaling, we sought to understand how calcium signaling was affected by Asic3 deletion and found that the STIM1 level, a key mediator of calcium influx, was notably increased in LICs, as well as in YFP+ BM leukemia cells." (PMID 41392978, 2025).
diabetes (2 papers, 2018 to 2024). "HK3, FCN1,CAMK1, GLUT1/SLC2A1 and GLUT3/SLC2A3 are involved in glucose and insulin metabolism that played vital role in development of obesity and diabetes." (PMID 29876008, 2018). "CAMK1, GLUT1/SLC2A1 and GLUT3/SLC2A3 genes were involved in glucose and insulin metabolism that played vital role in development of obesity and diabetes." (PMID 29876008, 2018).
ovarian carcinoma (2 papers, 2020 to 2022). A malignant neoplasm originating from the surface ovarian epithelium. "The mitochondrial fission protein, Dynamin related protein 1 (Drp1), and its upstream protein calcium/calmodulin–dependent protein kinase I (CaMKI) play a critical role in chemoresistance in ovarian cancer (OVCA)." (PMID 32448194, 2020).
pancreatic cancer (2 papers, 2021 to 2023). "The study found higher expression of CAMK1 in pancreatic cancer from bioinformatics as well as TMA‐IHC analyses." (PMID 38131168, 2023). "Herein, we explore the expressions and clinical significances of calcium/calmodulin‐dependent protein kinase 1 (CAMK1) in pancreatic cancer (PC)." (PMID 33342045, 2021). "Correlation between CAMK1 expression and clinicopathological characteristics of pancreatic cancer patients in the TMA‐IHC cohort." (PMID 33342045, 2021).
cardiac hypertrophy (1 paper, 2016). "Therefore, we focused on deciphering and discussing their regulatory roles in cardiac hypertrophy in the following sections and 5 focused NFAT associated genes (PLCE1, PPP3R1, PPP3CB, CAMK1, MEF2C) were studies for experimental validation." (PMID 27907007, 2016). "Notably, the expression patterns of PPP3CB, PPP3R1, PLCE1, MEF2C and CAMK1 in the “NFAT in cardiac hypertrophy” pathway played a significant role in the activation of hypertrophy of atrial myocytes in MR patients compared to normal subjects." (PMID 27907007, 2016).
lung carcinoma (1 paper, 2015). "CaMK1 appears to be tightly controlled by LILRB2/SHP2 signaling in lung cancer cells." (PMID 26056041, 2015). "Mechanistic analyses indicated that ANGPTL2 binds LILRB2 to support the growth of lung cancer cells and that the SHP2/CaMK1/CREB axis controls the proliferation of lung cancer cell lines." (PMID 26056041, 2015).
pulmonary heart disease (1 paper, 2024). "Calcium/calmodulin‐dependent protein kinase I (CAMK1) is associated with pulmonary heart disease." (PMID 38830831, 2024). "However, the mechanisms and functions of CAMK1 involved in cardiopulmonary diseases remain unclear." (PMID 38830831, 2024).
tumor (8 papers, 2014 to 2025). "These cells, which were overexpressed CaMK1, cause tumor cell growth similar to levels of untreated A549 cells indicating that CaMK1 rescued the LILRB2 deficiency." (PMID 26056041, 2015). "As KISS1R, KSR1, CAMK1, and SSPN have been either previously implicated in tumor cell migration or are known to participate in extracellular matrix adhesion, we wanted to explore whether any of these factors mediate RCC cell invasiveness." (PMID 24979721, 2014). "Considering the results of prognostic value of CAMK1 in database, we further validated the prognostic value of CAMK1 expression by using TMA‐based IHC in 90 paired PC tissues and corresponding adjacent non‐tumour tissues." (PMID 33342045, 2021). "Of these, we further establish a role for CDH13 in tumor angiogenesis, as well as a pro-migratory role for four novel factors including KISS1R, KSR1, CAMK1, and SSPN in ccRCC." (PMID 24979721, 2014). "Immunohistochemistry (IHC) of ccRCC tumor tissue microarrays (TMA) for CAMK1 and SSPN demonstrated non-specific staining and could not be quantitatively analyzed." (PMID 24979721, 2014).
cancer (6 papers, 2009 to 2025). A tumor composed of atypical neoplastic, often pleomorphic cells that invade other tissues. "Based on the GEPIA 2 database, Oncomine database and the HPA database, we demonstrated that compared to adjacent non‐cancer tissues, CAMK1 was highly expressed in PC tissues." (PMID 33342045, 2021). "Moreover, the IHC score showed CAMK1 protein levels were up‐regulated in PC tissues compared to the corresponding non‐cancer tissues." (PMID 33342045, 2021). "Several other interesting candidate genes were also identified such as CAMK1, STK6, PANK2 and EPHB1, all of which have been previously reported as being involved in cancer." (PMID 19519883, 2009). "Moreover, we implicate several of these gene hits not only in ccRCC for the first time (BHLHB3, CAMK1, CDH13, ENPP3, KCNJ2, KSR1, PLOD2, and TCF8), but also in a cancer model for the first time (CEP290, EFCAB3, PGBD5, RAPGEF5, SSPN, and TOX2)." (PMID 24979721, 2014). "Interestingly, four proteins that were upregulated by cancer were not detectable at all in the control (Ctrl) hippocampal protein samples, that is, Gpt1, Anillin, Camk1 and Cavin1." (PMID 40172096, 2025).
infection (2 papers, 2015 to 2024). The state of being infected such as from the introduction of a foreign agent such as serum, vaccine, antigenic substance or organism. "Furthermore, we showed that CaMK1 or CaMK2 silencing of hot pepper plants exhibited reduced HR lesions upon TMV-P0 infection." (PMID 25613640, 2015). "In particular, CaMK1 gene expression level was highly increased by TMV-P0 inoculation at 24 h and slightly induced upon PMMoV-P1,2,3 infection." (PMID 25613640, 2015). "To elucidate CaMK1 and CaMK2 function in L-mediated resistance, we checked whether CaMK1 and CaMK2 could be induced specifically during HR upon TMV-P0 infection using qRT-PCR." (PMID 25613640, 2015). "Thus, CaMK1 and CaMK2 are responsive genes to TMV-P0 infection." (PMID 25613640, 2015).
CAMK1 also shares sentences with these, for which no sentence is quoted: brain tumor (2 papers); breast carcinoma (2); endometrial carcinoma (2); medulloblastoma (2); acute leukemia (1); Alzheimer disease (1); aortic valve disease (1); autism (1); dementia (1); depression (1); epilepsy (1); hematological disease (1); hepatocellular carcinoma (1); myeloid leukemia (1); Obesity (1); schizophrenia (1); tauopathy (1).